RASL11A (RAS like family 11 member A)
Description:
Regulator of rDNA transcription. Acts in cooperation UBF/UBTF and positively regulates RNA polymerase I transcription (By similarity).
Tractability: No criterion of Open Targets' tractability assessment is met for any kind of drug.
Gene: Protein-coding gene on chromosome 13 (27,270,810 to 27,275,192, forward strand). Ensembl gene ENSG00000122035.
Subcellular location: Nucleus, nucleolus
Subcellular location (Human Protein Atlas): Nuclear bodies
Gene Ontology:
Molecular function: protein binding; GTPase activity; G protein activity; GTP binding
Biological process: positive regulation of transcription by RNA polymerase I
Cellular component: nucleolus
Genetic constraint (gnomAD): Loss-of-function variants: 18 observed, 20.92 expected, observed/expected ratio (o/e) 0.86, 90% interval 0.59 to 1.28. The upper end of that interval is the gene's LOEUF score, 1.28, which puts it in group 5 of 6, group 1 being the genes least tolerant of losing a copy. Missense variants: 283 observed, 312.98 expected, observed/expected ratio (o/e) 0.9, 90% interval 0.82 to 1. Synonymous variants: 146 observed, 132.82 expected, observed/expected ratio (o/e) 1.1, 90% interval 0.96 to 1.26.
Homologues: Orthologues: chimpanzee RASL11A (100% identical), macaque RASL11A (99% identical), dog RASL11A (93% identical), pig RASL11A (92% identical), rabbit RASL11A (91% identical), rat Rasl11a (91% identical), guinea pig RASL11A (90% identical), mouse Rasl11a (89% identical), tropical clawed frog rasl11a (68% identical). Paralogues in human: RASL11B (51% identical), RERG (31% identical), RERGL (31% identical), RASL12 (29% identical), RIT1 (26% identical), RAP1B (25% identical), RAP1A (25% identical), RRAS2 (25% identical), REM1 (24% identical), RASD2 (24% identical), REM2 (24% identical), RRAD (24% identical), and 23 more.
Diseases named in the same sentence as RASL11A in open-access papers:
RASL11A is named in the same sentence as 9 diseases in open-access papers, as found by Europe PMC text mining. Sharing a sentence is not in itself a finding about the gene and the disease. The quoted sentences say what the papers report.
colon cancers (1 paper, 2025). "RASL11a was expressed in regressed DFTD tumors but silenced in non-regressed tumors, consistent with homologous RASL11a downregulation in human prostate and colon cancers." (PMID 40991568, 2025).
colorectal cancer (1 paper, 2016). A primary or metastatic malignant neoplasm that affects the colon or rectum. "Additionally, the mutational frequency was >10% in 8 other TSGs in colorectal cancer: FAT4 (19%), TOPORS (15%), PPP2CB (13%), RASL11A (13%), PCDH9 (12%), PRDM2 (12%), LIFR (11%) and TGFBR2 (11%)." (PMID 26590405, 2016).
colorectal tumors (1 paper, 2025). "The expression of RASL11A in primary colorectal tumors is lower than in normal mucosa." (PMID 40564276, 2025).
tumor (6 papers, 2008 to 2025). "In tumors, a single point mutation in the 5′ untranslated region of RASL11a, a putative tumor suppressor, contributed to tumor regression." (PMID 40991568, 2025). "Confirming the putative function of this candidate gene, in vitro cell culture assays showed that overexpression of RASL11a slowed tumor growth relative to wild-type cell lines." (PMID 40991568, 2025). "RASL11A is intriguing as it was identified as a member of Ras super‐family with a possibility of being a tumor suppressor." (PMID 37641472, 2023). "In addition, the expression of RASL11A in the tumours, stimulating the Rat sarcoma pathway, has been connected to documented tumour regressions." (PMID 37255207, 2023). "Analysis of our RNA‐seq data and published RUNX3 ChIP‐seq data suggested that RASL11A might play a role in the tumor‐promoting ability of the exp‐CAFs and that it is under the control of RUNX3 at the transcription level." (PMID 37641472, 2023). "Further studies are required to elucidate whether and how RASL11A and the oxidative phosphorylation pathway influence the tumor‐promoting ability of CAFs." (PMID 37641472, 2023). "Others genes in this cluster were targets of estrogen action (e.g. T-type calcium channel subunit; CACNA1G), capable of binding estrogen receptor alpha (FASN, SNCG), or involved in tumor suppression (PRKCD, RASL11A)." (PMID 18941504, 2008). "However, evidence that RASL12 functions as a small GTP-binding protein is lacking; In fact, studies have reported that RASL12 could be homologous to the RAS-like GTPases RERG, RASL11A, RASL11B, RASL10A and RASL10B, which play tumor-suppressive roles in human cancers." (PMID 34819106, 2021).
RASL11A also shares sentences with these, for which no sentence is quoted: cancer (2 papers); breast carcinoma (1); breast tumors (1); lymph node metastases (1); prostate carcinoma (1).